PTN (pleiotrophin)
Diseases named in the same sentence as PTN in open-access papers (continued):
Sharing a sentence is not in itself a finding about the gene and the disease.
tumor (continued). "Previous studies have demonstrated that MK and PTN can be highly expressed in various human cancers and play a key role in the promotion of cancer cell survival, proliferation, and angiogenesis, contributing to tumor growth." (PMID 32153561, 2020). "In addition, PTN another gene effected by XIST is a heparin-binding growth factor that is involved with tumour progression." (PMID 33255394, 2020). "PTN is involved in cell growth, differentiation, and tumor progression." (PMID 32085797, 2020). "In vitro and in vivo experiments confirmed that elevated expression of PTN could increase the malignant grade of tumor cells, whereas knockdown of PTN can effectively inhibit tumour cell growth, migration and invasion." (PMID 30635982, 2019). "Pleiotrophin (PTN) is involved in tumour progression, angiogenesis and metastasis." (PMID 30635982, 2019). "Pleiotrophin is overexpression in many tumours and affects many aspects of tumour biology." (PMID 30635982, 2019). "In multiple myeloma, tumor-derived pleiotrophin and macrophage colony-stimulating factor stimulate monocytes to induce the expression of EC markers, and the cells become transdifferentiated into ECs that incorporate into tumor blood vessels." (PMID 31600937, 2019). "Six articles reported the link of PTN expression and tumor size." (PMID 30427932, 2018). "PTN can serve as a promising biomarker to predict unfavorable survival outcomes, and it may be a potential target for tumor treatment." (PMID 30427932, 2018). "Recently, emerging evidence has demonstrated that PTN/PTPRZ1 signalling might be involved in the carcinogenesis of several cancers; PTPRZ1 interacts with its ligand PTN to mediate tumour cell growth and metastasis." (PMID 30497491, 2018). "Next we investigated whether disrupting PTN expression could abolish the tumour-promoting effect of MLCs in GSC xenografts." (PMID 28569747, 2017). "To address whether M2 TAMs exert their tumour-promoting effect through PTN, we examined the potential co-distribution between PTN and GSCs in serial sections of human GBM specimens." (PMID 28569747, 2017). "PTN expression was significantly higher in tumour samples than in control samples, which was especially evident in HBV‐positive tumour tissues, and the inhibition of HBV replication could down‐regulate the expression of PTN." (PMID 28557334, 2017). "PTN expression was up‐regulated in HCC tissues compared with adjacent non‐tumour tissues, and HBx could regulate PTN expression by inhibiting miR‐384." (PMID 28557334, 2017). "Moreover, blocking the PTN–PTPRZ1 signalling by shRNA or anti-PTPRZ1 antibody potently suppressed GBM tumour growth and prolonged animal survival." (PMID 28569747, 2017). "Increased PTN expression has been reported in multiple tumour types." (PMID 28557334, 2017). "We hypothesized that the differing roles of PTN in lipid metabolism resulted from differences in β‐catenin between tumour cells and normal cells." (PMID 28557334, 2017). "In addition, PTN was negatively regulated by miR-384 in PTC cells, and overexpression of PTN attenuated the tumor-suppressive effects of miR-384 in PTC cells." (PMID 29299168, 2017). "To address whether the M2 TAM-secreted PTN functions as a paracrine factor to promote GSC tumour growth, we investigated whether silencing PTN expression in the M2-like TAMs could attenuate the pro-tumorigenic effect of TAMs on GSC-driven tumour growth." (PMID 28569747, 2017). "Disruption of PTN–PTPRZ1 signalling potently inhibits GSC-driven tumour growth, indicating that therapeutic targeting of PTN–PTPRZ1 signalling may effectively improve treatment for GBMs and potentially other malignant tumours." (PMID 28569747, 2017). "Recently, PTN overexpression has been detected in various tumor tissues, and may be clinically significant for cancer patients." (PMID 28969035, 2017). "A subsequent rise in PTN serum levels would suggest residual tumour recurrence." (PMID 28557334, 2017).
tumor (continued). "Interestingly, surface NCL is also a receptor for various molecules including cytokines (like midkine and pleiotrophin), vascular-targeting factors (endostatin and tumour-homing peptide F3) and some glycosaminoglycans." (PMID 25938538, 2015). "It is thought that PTN is an angiogenic factor thatstimulates tumor growth and metastasis." (PMID 22496782, 2012). "Finally, we investigated the PEI/siRNA-mediated knockdown of the tumor-relevant growth factor pleiotrophin (PTN) in an in vivo tumor model." (PMID 27721338, 2011). "We have preliminary evidence that anti-VEGF therapy can influence PTN expression and signaling and anticipate that combination of anti-VEGF with anti-PTN therapy will dramatically augment anti-tumor effects by reducing angiogenesis and improving the immunogenicity of tumor cells." (PMID 24281102, 2010). "Specific inhibitors of the VEGF:VEGFR2 interaction significantly increase PTN expression in three separate pre-clinical tumor models, suggesting that VEGFR1 signaling may be important in this phenomenon." (PMID 24281102, 2010). "The function of PTN in tumor angiogenesis has been addressed to some extent." (PMID 20565841, 2010). "Importantly, we identified tumour cells of IBC that specifically express the heparin-binding growth factor PTN, the ligand for which is widely expressed in multiple cell types of IBC and the expression scores correlated strongly with the immunosuppressive status of the various cell types." (PMID 40624675, 2025). "This suggests that PTN might also contribute to early tumor development." (PMID 36828390, 2023). "Moreover, CTGF+ CAFs may further impact tumor-associated macrophages (TAMs) by the M2-type macrophages through ligand-receptor molecules, such as SPP1-CD44, PTN-NCL, and MDK-NCL." (PMID 35894206, 2022). "In addition, the PITPNA‐AS1/miR‐223‐3p/PTN axis accelerated tumor development in vivo." (PMID 35588441, 2022). "However, the exact molecular mechanisms underlying TAMs' functions in promoting GSC maintenance and GSC-driven tumor growth remain largely unknown, except for a few studies reporting molecules, e.g., TGFβ1 18 and PTN 27 were specifically involved." (PMID 35673564, 2022). "Importantly, we found that PTN was significantly correlated with disease stages, suggesting that PTN may be a valuable marker for predicting tumour progression in SCLC patients." (PMID 30635982, 2019). "Increased PTN expression could promote tumour proliferation and angiogenesis in vivo." (PMID 28557334, 2017). "PTN expression correlated significantly with the necrosis rate (p=0.003) and local tumor recurrence (p=0.001), but not with other clinical features including gender (p=0.924), age (p=0.274), tumor location (p=0.472), lung metastasis (p=0.109) and TNM stage (p=0.135)." (PMID 28969035, 2017). "In addition, PTN is a proto-oncogene expressed in malignant tumors and cell lines of various organs such as breast, prostate, colon, lung and skin and is thought to be involved in tumor angiogenesis and metastasis." (PMID 22496782, 2012). "Therefore, PTN may indirectly affect Tregs in the tumor microenvironment through modulation of macrophage infiltration and phenotype." (PMID 24281102, 2010). "In addition to the clinically relevant finding that PTN is detectable in the serum of tumour patients, it is important to ascertain whether the source of PTN production is the tumour itself." (PMID 11953815, 2002). "Spatial mapping revealed spatial association of RCC progression-associated cancer and immune cell subpopulations, suggesting the potential role of the VEGF, GDF, PTN and IL16 pathways in the remodeling of the tumor microenvironment." (PMID 42196432, 2026). "This study aims to identify novel regulatory targets and signaling pathways that modulate the tumor microenvironment (TME) in HGSOC, focusing on the pleiotrophin (PTN) signaling pathway and syndecan 4 (SDC4) expression as potential biomarkers for prognosis." (PMID 40416874, 2025).
tumor (continued). "Single-cell communication analyses identified unique signaling axes, including PTN–NCL and COL4A1–CD44, which were exclusive to high-REN-expressing tumor cells and their NK cell interactions." (PMID 40534868, 2025). "Compared to the intercellular interactions in normal tissues, we noted several tumor-promoting signaling pathways specificly found in PCa tissues, including ANGPTL, FN1, GDF, CSF, PTN, and LAMININ signaling pathways." (PMID 40438108, 2025). "Through comprehensive bioinformatics analysis, we identified PTN signaling as a key mediator of intercellular communication within the TME, influencing various cellular interactions that contribute to tumor progression." (PMID 40416874, 2025). "PTN is a PDGF-inducible cytokine, secreted by various human cancer cells and promotes tumorigenesis, tumor growth, as well as tumor angiogenesis." (PMID 40069574, 2025). "In the context of PTN and COLLAGEN signaling, both NK and T cells were major recipients of these outgoing signals, while fibroblasts and high-REN-expressing tumor cells acted as major producers of the signaling molecules." (PMID 40534868, 2025). "We found that macrophages, which served as the source cells of tumor, showing stronger interaction strength with other cell types, especially fibroblasts and hepatocytes, and the SPP1, PTN, CCL, TGFB1 and PLAU pathways were more enriched in tumor regions." (PMID 40230843, 2025). "Key pathways involved include MDK, PTN, SPP1, and FN1, all of which play central roles in immune regulation and tumor progression." (PMID 40837013, 2025). "By leveraging specific ligand-receptor interactions, such as PTN-NCL and COL4A1-CD44, tumor cells impose a regulatory influence on NK cells while bypassing significant engagement with T cells or fibroblasts." (PMID 40534868, 2025). "For example, in C7 and C8 tumor clusters, outgoing pattern 1 coordinates signals like MK, EGF, PTN, GDF, and EDN." (PMID 38191424, 2024). "On the other hand, the communication patterns of the target cells suggested that incoming tumor epithelial cell signalings were dominated by mode 1, which included signaling pathways such as CD99 and MK, as well as PTN, CEACAM, CD96, and GRN." (PMID 38482016, 2024). "Based on our findings, we observed that PLOD2 + SAA1 + tumor cells were able to communicate with TME cells and act as strong senders and influencers in signaling pathways such as SPP1, MIF, PTN, and MK." (PMID 38951896, 2024). "This revealed several strong putative interactions between GBM tumor cell ligands and macrophage receptors that were conserved over the different co‐cultures, including APP:CD74, CD99:PILRA, PTN:ALK, and CLU:TREM2." (PMID 37791581, 2023). "Increased expression of 1 of the differentially expressed genes between group 1 and 2, pleiotrophin (PTN), appeared to correlate with a more aggressive tumor phenotype." (PMID 37691636, 2023). "The interaction pairs via SPP1, RARRES2, NECTIN3, LGALS9, and LAMB1 showed increased signaling in the autophagy-high tumor cells, while SEMA3C, PTN, ICAM1, GAS6, and CSF1 showed decreased signaling compared with those in the autophagy-low tumor cells." (PMID 36830707, 2023). "Our volcano plot and GO analysis showed the significant downregulation of tumor-suppressive genes, such as ANOS1, CDH11, COL4A5, POSTN, PTN, and BEX1 in As- transformed cells, which is considered an early event of carcinogenesis." (PMID 35954277, 2022). "For instance, pleiotrophin (PTN) secreted by TAMs binds to PTPRZ1 on GSCs, resulting in their activation and consequently tumor growth." (PMID 33766119, 2021). "snRNP70 was less abundant in the perilesional region than in tumor area (p=0.0046) although OLIG2 and PTN were expressed at similar levels in the corresponding samples." (PMID 35047379, 2021). "Five of these signaling proteins (CDKN1B, CDKN1C, PTN, GJA1, and MORF4L2) can act as tumor suppressors." (PMID 32168333, 2020).
tumor (continued). "Univariate cox regression analysis revealed that 14 genes within the hot subnetworks showed expression pattern significantly correlated with patients’ overall survival, including PTN and EGFR, two major players in tumor progression." (PMID 32231683, 2020). "We and others, previously demonstrated that GSCs migrate from the tumor mass toward the SVZ, through the CXCL12/CXCR4 axis or through a pleiotrophin-driven axis." (PMID 33575218, 2020). "The transcription factor can bind with PTN (Pleiotrophin) or FGFBP1 (Fibroblast growth factor-binding protein 1) promoter, which are crucial for tumor growth and then inactivates them." (PMID 31121863, 2019). "The high expression of PTN is significantly relevant to the advanced TNM stage and poor OS in tumor patients." (PMID 30427932, 2018). "Our previous study demonstrated that PTN and PTPRZ1 were highly expressed in recurrent TNBC tissue, which hinted at their tumour-promoting effects." (PMID 30497491, 2018). "We demonstrated that the expression of PTN and PTPRZ1 was upregulated by chemotherapy, and this change in expression decreased chemosensitivity by promoting tumour proliferation and inhibiting apoptosis." (PMID 30497491, 2018). "Meanwhile, disrupting PTN in MLCs reduced the proportion of SOX2+ tumour cells in the xenografts co-implanted with GSCs and shPTN MLCs (P<0.01, ANOVA test), suggesting that TAM-secreted PTN promoted GSC maintenance." (PMID 28569747, 2017). "Our study uncovered that CD11b+/CD163+ M2 TAMs promote GSC maintenance and GSC-driven tumour growth through the PTN–PRPTZ1 signalling, demonstrating that PTN is a critical molecular mediator bridging TAMs and GSCs in GBM tumour microenvironment." (PMID 28569747, 2017). "We revealed that the TAM-secreted PTN acts through PTPRZ1 on GSCs to promote the self-renewal and tumour propagation of GSCs." (PMID 28569747, 2017). "Collectively, these data demonstrate that disrupting PTN–PTPRZ1 signalling by the anti-PTPRZ1 antibody impairs the supportive effect of TAMs, thus potently suppresses GSC tumour growth." (PMID 28569747, 2017). "We found that a heparin-binding glycoprotein pleiotrophin (PTN) was consistently and preferentially secreted by the CD11b+/CD163+ TAMs to promote GSC tumour growth." (PMID 28569747, 2017). "IHC staining of PTN, the GSC marker SOX2 and the M2 TAM marker CD163 revealed that tumour regions with high levels of PTN expression and CD163+ M2 TAM infiltration contained abundant GSCs marked by SOX2." (PMID 28569747, 2017). "In this study, we uncover that M2 TAMs preferentially secrete the cytokine PTN to impact GSCs through its receptor PTPRZ1 to promote GSC maintenance and tumour growth." (PMID 28569747, 2017). "PTN and MDK are overexpressed in various human cancers, where they are thought to promote cell survival, proliferation and angiogenesis, contributing to tumor growth." (PMID 26914549, 2016). "PTPRZ1 interacts with its ligand pleiotrophin (PTN), which is a secreted growth factor involved in angiogenesis and tumor growth." (PMID 23170925, 2012). "Further experiments are needed to address the possibility of PTN mediating its effects via ALK in SCLC cells, the effects of PTN deletion on tumor growth, and the mechanism of PTN/PTPRZ1 autocrine regulation in NET cells." (PMID 23170925, 2012). "The mean serum PTN concentration was 6909 pg ml−1 (n=10) in patients with tumour stage IIB/IIIA and 19944 pg ml−1 (n=12) in patients with tumour stage IIIB/IV." (PMID 11953815, 2002). "Additionally, the SVZ was found to drive GBM invasion through the secretion of various chemical factors, such as pleiotrophin (PTN) complexes and C-X-C motif chemokine 12 (CXCL12), inducing angiogenesis and providing nutrients for tumor growth." (PMID 39935607, 2025). "Additionally, M2 TAMs can secrete factors like pleiotrophin (PTN) that interact with receptors on cancer stem cells, endowing tumor cells with stem-like properties and further increasing resistance and metastatic potential." (PMID 40787471, 2025).
tumor (continued). "Further, we found that the density of CD44+ and CD44+PTN+ tumor cells increased progressively from the tumor center towards the periphery, supporting our previous findings that CD44+ cells at the tumor leading edge secrete high levels of PTN." (PMID 40069574, 2025). "Notably, tumor cells with high REN expression exhibited distinct differences in cellular communication patterns with NK and T cells, especially through PTN and COLLAGEN signaling pathways." (PMID 40534868, 2025). "Single-cell analysis revealed that HOXA5+ malignant cells enhance communication with fibroblasts and endothelial cells via IGFBP3-TMEM219 signaling, while HOXA5+ fibroblasts reshape the immune microenvironment via PTN-NCL, providing mechanistic insights into its tumor-promoting roles." (PMID 41209012, 2025). "CD163+ TAMs secrete pleiotrophin (PTN), which binds to its receptor on GSCs, protein tyrosine phosphatase receptor type Z1 (PTPRZ1), promoting self-renewal and sustainability that support tumor progression." (PMID 40361384, 2025). "For EGFRvIII(+) GBM patient single-cell data, the pattern analysis results showed that in the outgoing pattern analysis, tumor cells dominated Pattern3, with the MDK signaling pathway being the most active in Pattern3, followed by the PTN and SPP1 signaling pathways." (PMID 40527884, 2025). "In C8 and C9 tumor clusters, incoming pattern 1 coordinates signals like MIF, ANGPTL, MK, and PTN." (PMID 38191424, 2024). "From a therapeutic standpoint, targeting the PTN-NCL signaling axis may provide an innovative approach to inhibit CAF formation and thereby attenuate tumor aggressiveness." (PMID 39759507, 2024). "Additionally, when the tumor group acted as the recipient, we observed a stronger effect of the SPP1-CD44 axis and the PTN-SDC series axis in the M1-high group." (PMID 39707474, 2024). "An increase in PTN levels enhances the cell surface localization of NCL, which may be related to interactions in the tumor microenvironment." (PMID 38806553, 2024). "For example, pathways of VEGF, non-canonical WNT, and pleiotrophin, which were important for the growth of tumor cells, were enriched in stage I CRC." (PMID 37360193, 2023). "Likewise, our data showed HER2low TNBC actively participated in activities with regard to tumor metabolism and growth pathways with MUCL1, PTN, SCGB2A2 and APOD highly expressed, revealing an increased metabolic and proliferative capacity contained." (PMID 36998014, 2023). "Interestingly, there was visually apparent co-localization of tumor neuroectoderm-like cells with high PTPRZ1, PTN, and FGFR3, identified as important for neuroectoderm-like neoplastic cell signaling as above." (PMID 36966348, 2023). "It is intriguing that the absence of PTN slows spontaneous primary tumor growth in Ptn-null mice but fails to affect primary tumor growth when 3B10 treatment is initiated once tumors are established." (PMID 36828390, 2023). "Additionally, the secretion of pleiotrophin by CD163+ TAMs in glioma fostered CSC-mediated tumor growth and the inhibition of this pathway led to decreased tumor growth and prolonged survival in mouse xenografts." (PMID 32117287, 2020). "Additionally, we investigate the correlation of PTN levels and adverse clinic features of SCLC such as tumor stage." (PMID 30635982, 2019). "PTN (Pleiotrophin) could restrain the differentiation of epithelial cells in vivo and TGFB3 (Transforming growth factor-β 3) was shown to have tumor-suppressing function." (PMID 29190897, 2017). "Disrupting the PTN–PTPRZ1 signalling by shRNA or the antibody blockade against PTPRZ1 largely abrogates the tumour-supportive effects of PTN and suppresses GBM growth driven by the tumour-initiating GSCs." (PMID 28569747, 2017). "To evaluate the therapeutic potential of targeting the PTN–PTPRZ1 paracrine signalling in GBM treatment, we examined whether a specific anti-PTPRZ1 antibody could inhibit GSC-derived tumour growth." (PMID 28569747, 2017).